CDC20 (cell division cycle 20)
Diseases named in the same sentence as CDC20 in open-access papers (continued):
Sharing a sentence is not in itself a finding about the gene and the disease.
tumor (continued). "Furthermore, treatment with omaveloxolone reduced tumour volume and downregulated the expression of CDC20 in vivo, indicating the potential of omaveloxolone as a therapeutic anticancer agent." (PMID 40439120, 2025). "They suggested CDC20 as a potential biomarker for tumor prognosis and a therapeutic target." (PMID 39795587, 2024). "The tumor weight and volume in the apcin combined with the IR group were markedly lower than those in the other treatment groups, indicating that inhibition of CDC20 activity increased radiosensitivity in vivo." (PMID 39125953, 2024). "Furthermore, the Human Protein Atlas was used to validate the upregulated expression of the CDC20 gene using IHC images for CDC20 protein in tumor and normal breast tissue." (PMID 39061186, 2024). "In support of its oncogenic function, CDC20 depletion leads to effective tumor regression." (PMID 39114311, 2024). "Furthermore, a comparison of CDC20 expression between normal and tumor tissues in TCGA and GSE31210 cohorts showed significantly higher expression in tumor tissues." (PMID 39114311, 2024). "As CDC20 is a key activator in the Anaphase-Promoting Complex/Cyclosome (APC/C), an E3 ubiquitin ligase, it remains unclear whether CDC20 influences DNA damage repair via ubiquitination mechanisms and thus affects drug resistance in tumor cells." (PMID 39125953, 2024). "In conclusion, the findings of this study suggest that CDC20 may be involved in immunomodulating the tumor microenvironment and provide evidence that CDC20 inhibition may serve as a potential therapeutic approach for the treatment of BC patients." (PMID 39061186, 2024). "In vivo experiments demonstrated that knocking down CDC20 inhibited tumor formation." (PMID 39114311, 2024). "Overall, these results strongly suggest a high correlation between CDC20 and tumor malignancy." (PMID 39114311, 2024). "To determine whether CDC20 inhibitors could enhance radiosensitivity in vivo, we conducted a tumor xenografth model in athymic nude mice." (PMID 39125953, 2024). "In support of this hypothesis, we observed a statistically significant increase in tumor growth of the A3 CDC20 promoter indel cell line relative to the parental A375 cell line when subcutaneously xenografted in the flanks of immunocompromised nude mice." (PMID 38030698, 2023). "CDC20 overexpression was also closely related to poor pathological classification and shorter survival in these tumor patients, suggesting that it might serve as an important prognostic factor and a potential anti-tumor target." (PMID 36882855, 2023). "CDC20 maybe an oncogenic role in patients with primary cSCC, and its expression was significant upregulated in cSCC which correlated with tumor differentiation." (PMID 37325059, 2023). "Furthermore, our data collectively demonstrated that the role of CDC20 depletion in enhancing the infiltration of anti-tumor immune cells, particularly CD8+ T lymphocytes, and this effect is dependent on the presence of GSDME." (PMID 37528490, 2023). "Interestingly, the growth rates were markedly faster for A3 compared to wild-type in the in vivo study than as assessed by the in vitro cell viability assay, suggesting an important interaction between the tumor microenvironment and CDC20 function." (PMID 38030698, 2023). "Furthermore, in our syngeneic murine models, we found that depletion of CDC20 significantly enhances the anti-tumor immunity by promoting the infiltration of CD8+ T lymphocytes dependent on the existence of GSDME, as well as reducing myeloid immune cells." (PMID 37528490, 2023). "Therefore, we have summarized several CDC20 inhibitors with therapeutic effectiveness in suppressing tumor progression." (PMID 37682144, 2023). "In this study, apcin treatment attenuated cell proliferation, migration and invasion, enhanced cell apoptosis, and induced G2/M arrest, explaining that CDC20 inhibition could exert anti-tumor activity in MCL." (PMID 36882855, 2023).
tumor (continued). "Notably, CDC20 also promotes angiogenesis in tumor tissues by regulating EMT and VEGF expression, which is an important pathway promoting invasion and metastasis." (PMID 37682144, 2023). "Rottlerin exert its tumor suppressive function by inhibiting CDC20 expression." (PMID 37682144, 2023). "Cdc20-kd leads to mitotic arrest and apoptosis in various tumor cell lines." (PMID 35832196, 2022). "CDC20 is overexpressed in tumor cells and acts as a poor prognostic factor in multiple cancers." (PMID 35875060, 2022). "cdc20 is usually considered as an oncogenic factor that promotes tumor development." (PMID 36316768, 2022). "The results showed that the higher tumor grade, the higher CDC20 expression in HCC." (PMID 35622386, 2022). "In addition, silencing CDC20 expression in tumor-initiating cells accelerated a significant increase in apoptotic cell death." (PMID 36238156, 2022). "Both play a role in tumorigenesis with Cdh1 being a tumor suppressor and Cdc20 an oncogene." (PMID 35832196, 2022). "In addition, CDC20 is an essential cell cycle regulator, it can promote the development of tumor by inhibiting apoptosis and affect RCC formation." (PMID 36098680, 2022). "Dysregulation of the CDC20–hnRNPU axis contributes to tumor progression and drug resistance." (PMID 35954396, 2022). "The cellular function implies that CDC20 may be a potential target for tumor-targeted therapy development." (PMID 35859798, 2022). "As CDC20 expression correlated with CAFs and MDSCs, it is proposed that the anti-tumor effects of targeting Cdc20 could be augmented by the immune system." (PMID 34527589, 2021). "Thus, CDC20 suppression can be resulted to the arrest of the cell cycle and thereby reduction of the tumor progression." (PMID 34681181, 2021). "The knockdown of Cdc20 dramatically inhibited tumor growth both in vivo and in vitro." (PMID 34527589, 2021). "In addition, the anti-tumor activity of a potential CDC20 inhibitor, namely dinaciclib, was investigated in CCA cell lines." (PMID 33777535, 2021). "It was also proved that CDC20 was a great target for anti-tumor drug development." (PMID 34686627, 2021). "By using GO function and KEGG analyses, survival analysis, ROC curve analysis, and representative image analysis of CDC20, our findings demonstrate that CDC20 may play a role in early diagnosis, tumour stage, and poor outcomes of HBV-HCC." (PMID 34603487, 2021). "In addition, four genes (CDC20, UCK2, HEATR6, and SLC9A3R2) were concordantly associated with both survival duration and tumor progression (3.2)." (PMID 34858848, 2021). "Furthermore, the abundance of phosphorylated Cdc20 in the primary tumor was elevated and correlated with increased tumor grade." (PMID 34527589, 2021). "As a result, the overexpression of the CDC20 gene in malignant tissues could be a general biological alternation in the tumor, which further supports the oncogenic role of CDC20." (PMID 34527589, 2021). "Interestingly, the expression levels of phosphorylated Cdc20 in the primary tumor were predominantly increased in primary tissue, with a higher fold change compared with the Cdc20 total protein." (PMID 34527589, 2021). "Collectively, CCNA2, CDK1, and CDC20 may serve as promising biomarkers for HB and provide prospects for designing targeted therapies using synthetic inhibitors as anti-tumor agents." (PMID 33718368, 2021). "Moreover, results from recent TCGA and pathological studies have demonstrated a pivotal oncogenic role for CDC20 in tumor progression as well as drug resistance." (PMID 34266348, 2021). "As a tumor-promoting factor, CDC20 plays an important role in regulating the cycle." (PMID 32848800, 2020). "Moreover, Apcin was found to bind directly to Cdc20, inhibiting the ubiquitylation of D-box-containing substrates, and subsequently inducing tumor cell death." (PMID 33643919, 2020).
tumor (continued). "Thus, either low or high expression of MAD2 or CDC20 can lead to aneuploidy and even tumor formation." (PMID 32066746, 2020). "To investigate whether the CDC20 gene acts as an oncogene in other tumours, we analysed the differential expression of CDC20 in different tumours and normal tissues through the TIMER website." (PMID 32047816, 2020). "HMMR and TPX2 were also negatively correlated to patients’ prognosis while no expression difference was observed in diverse tumor grades and CDC20 was positively associated with tumor grade but not correlated to patients’ outcomes." (PMID 32716025, 2020). "Similarly, BUB1B and CDC20 were both significantly up-regulated in PDAC patients with new tumor development after initial treatment (both P<0.05)." (PMID 30765611, 2019). "Moreover, overexpression of BUB1B, CCNA2, CDC20, and CDK1 in tumor tissues was significantly associated with disease-free survival (DFS) in PDAC patients (Log rank P=0.00565, P=0.0357, P=0.00104, and P=0.00121, respectively)." (PMID 30765611, 2019). "Collectively, these findings suggest that MAD2L1 and CDC20 may be key regulators of tumor severity, ultimately dictating patient survival." (PMID 30245591, 2018). "Next, to further investigate whether Cdc20 was involved in SPRY4-IT1-mediated tumor progression, we performed a rescue assay." (PMID 29489909, 2018). "Consistently, downregulation of Cdc20 promoted curcumin-mediated anti-tumor activity." (PMID 28165402, 2017). "Similarly, silencing the expression of Cdc20 by liposomally-encapsulated Cdc20 siRNA inhibited tumor growth via induction of apoptosis of the tumor endothelial cells." (PMID 28165402, 2017). "Thus our findings have elucidated that Cdc20-mediated proteasomal degradation of SMAR1 limits its tumor suppressive activity." (PMID 28617439, 2017). "Moreover, Cdc20 expression was positively correlated with clinicopathological parameters including invasion, and pathological tumor status." (PMID 27418942, 2016). "Particularly in serous epithelial ovarian cancer, overexpression of CDC20 is a prognostic factor associated with clinical stage of disease, irrespective of tumor grade." (PMID 23738901, 2013). "CDC20 is highly expressed in many tumor cells, where it results in chromosomal instability." (PMID 22475564, 2012). "UBE2C, CCNB1, CCNB2, PLOD2, NUP210, MELK, CDC20 genes were overexpressed in tumours and in CIN3/CIS relative to both Normal and CIN1/CIN2, suggesting that they could have a role to play in the early phase of tumorigenesis." (PMID 21338529, 2011). "UBE2C, CCNB1, CCNB2, PLOD2, NUP210, MELK, CDC20 were overexpressed in tumours and in CIN3/CIS relative to both Normal and CIN1/CIN2, suggesting that they could have an important role to play in the early phase of tumorigenesis." (PMID 21338529, 2011). "CDC20 appeared to be over-expressed in the majority of the tumor samples." (PMID 21483740, 2011). "Additionally, CDC20 protects diverse tumor cells from apoptosis." (PMID 40045239, 2025). "Furthermore, the lack of association with overall survival highlights the possibility that the prognostic relevance of CDC20 may be limited to certain subsets of patients with BC or specific tumor characteristics." (PMID 39795587, 2024). "In addition, CDK1, CDC20, CCNA2, CCNB1 and CCNB2 expressions may be involved in the regulation of monocytes and tumor-associated macrophages (TAMs) in HCC, respectively." (PMID 36605491, 2023). "The following sections summarize CDC20 functions, including mitosis-related and unrelated ones, and the available data sustaining the oncogenic impact of CDC20 in hematological malignancies in order to evaluate its potential role as prognostic factor and therapeutic target in these neoplasms." (PMID 35490245, 2022).
tumor (continued). "The specific knockdown of CDC20 by siRNA showed a suppressed effect against WT cell proliferation and migration in vitro, which indicated that the overexpression of CDC20 might be expected to accelerate cell proliferation and promote tumor initiation and progression of WT." (PMID 34513754, 2021). "CDC20, a key regulator in the cell cycle, is overexpressed in HCC and correlates with tumor characteristics and poor prognosis." (PMID 41511815, 2026). "Close correlations were observed between WDR77 and CDC20, WDR77 and tumor cells, and CDC20 and tumor cells." (PMID 41425556, 2025). "Increased CDC20, LPCAT1, and SPP1 and reduced PON1 were found in tumor tissues than normal tissues, as well as in advanced patients than early-stage patients." (PMID 40404896, 2025). "Six overlapping hub genes (CD8A, CDC20, E2F1, IL10, TNF, VCAM1) were overexpressed in GS 10 tumors, reflecting key pathways in tumor progression." (PMID 40227503, 2025). "Among these, seven genes, namely, RRM2, KIF11, ANLN, CDC20, YWHAZ, DTL, and PCNA, exhibited significantly elevated expression in tumor samples (p ≤ 0.05)." (PMID 41487287, 2025). "A study based on microarray data identified five genes (CDK1, CDC20, CCNB1, CENPF, and MAD2L1) related to the tumor stage, early diagnosis, and poor outcomes." (PMID 40282296, 2025). "The results of TCGA-LIHC dataset analysis showed that compared with normal tissues, CDC20, LPCAT1, and SPP1 were significantly up-regulated and PON1 was significantly down-regulated in tumor tissues." (PMID 40404896, 2025). "In GSE25097 dataset, compared with normal tissues, the expressions of CDC20, LPCAT1, and SPP1 were significantly upregulated, while PON1 was significantly downregulated in tumor tissues, which was consistent with the results in TCGA." (PMID 40404896, 2025). "Elevated CDC20 levels facilitate the ubiquitination and degradation of CDKN1B, a G1/S phase cell cycle inhibitor, driving GBM cell proliferation and tumor progression." (PMID 40565099, 2025). "Further, RNA-seq of BT549 cells after siKNSTRN revealed pronounced downregulation of critical cell cycle-related genes, including CDK2, CDC20, FOXM1, and E2F1, which have been documented to drive uncontrolled proliferation and tumor growth in TNBC." (PMID 41209020, 2025). "The expression levels of KIF2C, CENPA, CDC20, UBE2C, ESPL1, KIF23, and PLK1 were significantly higher in the tumor tissues of patients with a HOST-response compared to those without a HOST-response." (PMID 39201599, 2024). "Next, using machine learning, we identified and validated three hub genes (CDC45, CDC20, TPX2), with CDC20 showing the highest correlation with tumor stemness and limited previous research." (PMID 39114311, 2024). "Correlation analysis indicated a positive relationship between CDC20 expression and tumor grade (r = 0.284, p = 0.038) and between CCNB1 expression and tumor stage (r = 0.301, p = 0.027)." (PMID 39795587, 2024). "The significant enrichment of the “Cell cycle” pathway across these modules highlights the importance of CDK1 and CDC20 in NSCLC, as their dysregulation contributes to tumor aggressiveness and resistance to treatment." (PMID 39457373, 2024). "Among the 991 BC tumor samples, GATA3 had the highest frequency of somatic SNVs, accounting for 13%; followed by FOXA1, accounting for 3%; AGR2, CA12, CEP55, CDC20, TBC1D9, and MELK had very few somatic SNVs." (PMID 39440050, 2024). "HMGB2 in POSTN+ fibroblasts is predicted to bind to PLD2, LRP5, MYLK, and CD44 on tumor cells, regulating downstream genes, including BIRC5, CCNA2, CCNB1, CCNB2, CDC20, and MKI67, which are related to the cell cycle." (PMID 38519500, 2024). "The gene expression profiles suggested that the expression levels of CDC20, UQCRH, TIMM10, TIMM13, POLR2L, and NDUFAB1 were upregulated in tumor tissue." (PMID 36901944, 2023).
tumor (continued). "The result also showed that CDK1, CDK5, CDC20, CCNA2, CCNB1 and CCNB2 mRNA expression levels within tumor tissues were significantly increased compared with the adjacent normal tissues." (PMID 36605491, 2023). "In keeping with that, the markers for anti-tumor immunity, including CD44 and CD8A were significantly reduced in the CDC20-high group." (PMID 37528490, 2023). "Cell division cycle 20 (CDC20) regulates cell division and plays an important role in tumorigenesis and tumor progression." (PMID 35126643, 2022). "CDC20-APC is required for GSC self-renewal and invasiveness, and CDC20 overexpression enhances tumor growth in vivo." (PMID 35737702, 2022). "We have previously demonstrated that CDC20 is a critical determinant of GSC phenotypes, specifically invasiveness, self-renewal, and tumor growth." (PMID 35737702, 2022). "We identified three critical genes (FCN3, CDC20, and E2F1) involved tumor prognosis in HCC patients." (PMID 35402624, 2022). "CDC20 has been reported to be overexpressed in HCC tissues and positively related to the tumor, TNM stage, and ki-67 expression." (PMID 35875102, 2022). "Pharmacological inhibition of CDC20-APC/C by either CDC20 inhibitor Apcin or CDC20 PROTAC CP5V blocks mitotic progression and induces tumor cell death." (PMID 35954396, 2022). "Reduced CDC20 expression disrupts the APC-CDC20 interaction and shows great effect on suppressing tumor proliferating and metastasis." (PMID 35875060, 2022). "In this study, three key genes, CDC20, CCNB2, and BUB1, have been identified in youth-onset NSCLC tumor tissues based on the TCGA and GEO cohorts." (PMID 35859798, 2022). "We used flow cytometry to evaluate the effect of CDC20 inhibition on the apoptosis and cell cycle of HCC tumor cells." (PMID 34512169, 2021). "By using TCGA and THPA databases, we found five genes, CDK1, CDC20, CCNB1, CENPF, and MAD2L1, that were related to the early diagnosis, tumour stage, and poor outcomes of HBV-HCC." (PMID 34603487, 2021). "We also proved that the transcriptome data was consistent with the transcriptional abundance of Cdc20 by the CPTAC dataset, and the expression levels of phosphorylated Cdc20 in primary tumors were elevated and correlated with increased tumor grade." (PMID 34527589, 2021). "Intriguingly, the expression levels of CCNB1, CDC20, and CENPE in PBMCs were completely opposite to those observed in tumor tissues." (PMID 34660300, 2021). "CIN promotes tumor development primarily through the aberrant expression of the mitotic checkpoint proteins MAD2 and CDC20." (PMID 32066746, 2020). "Studies have reported that Cdc20 is a pivotal mitotic factor governing anaphase initiation, and Cdc20-APC/C is fast becoming highlighted as a key instrument in tumor progression." (PMID 33082784, 2020). "If CDC20 is involved in tumor formation, then we expected that the bulk of the tumor suppressors targeted by the APC would rely on CDC20 activity, whereas the tumor promoters should be specifically targeted by CDH1." (PMID 32805721, 2020). "We performed BioGRID analyses of the APC coactivators CDC20 and CDH1, which revealed that at least 69 proteins serve as APC substrates, with 60 of them identified as playing a role in tumor promotion and 9 involved in tumor suppression." (PMID 32805721, 2020). "In the present study, we identified nicotine as a stimulator of YAP nuclear localization, which enhanced the expression of YAP target genes (CDX2, CDC20, CTGF, and CYR61) and enhanced tumor growth." (PMID 32894161, 2020). "We further measured the expression levels of Cdc20, Ki67 and activate caspase-3 in the isolated grafted tumors using IHC analysis, and confirmed that CP5V reduced tumor growth by decreasing the Ki67 index in the tumor." (PMID 31669221, 2019).